RNU4-80P (RNA, U4 small nuclear 80, pseudogene)
Gene: Small nuclear RNA gene on chromosome 15 (59,212,648 to 59,212,788, reverse strand). Ensembl gene ENSG00000200070.
Homologues: Orthologues: chimpanzee U4 (98% identical), macaque U4 (92% identical), guinea pig U4 (77% identical), dog U4 (60% identical), rat LOC120096855 (60% identical), rabbit U4 (58% identical), dog U4 (54% identical). Paralogues in human: RNU4-68P (84% identical), RNU4-7P (83% identical), RNU4-13P (82% identical), RNU4-42P (82% identical), RNU4-44P (82% identical), RNU4-67P (82% identical), RNU4-31P (82% identical), RNU4-58P (81% identical), RNU4-76P (79% identical), RNU4-23P (79% identical), RNU4-56P (79% identical), RNU4-92P (79% identical), and 80 more.